IL10 (interleukin 10)
Diseases named in the same sentence as IL10 in open-access papers (continued):
Sharing a sentence is not in itself a finding about the gene and the disease.
infection (continued). "On the other hand, an enzymatic inhibitor of HO-1 provided mice with resistance to infection, decreasing IL-10 and FIZZ-1 transcript levels in liver." (PMID 28798750, 2017). "IL-10 is an immunoregulatory cytokine, which in other infections can control the expression of pro-inflammatory cytokines, but its role in melioidosis has not been addressed." (PMID 28216665, 2017). "The cytokine cascade events following B. pseudomallei infection has been studied in several animal models and show an up regulated mRNA expression of inflammatory cytokines such as IL6, IL12, IL10, IFNγ, TNFα and IL1β within 72 hours of infection." (PMID 28628607, 2017). "These events form a positive feedback loop whereby IL-10 further inhibits antimicrobial immune responses, allowing inevitably serious infections to develop." (PMID 29089927, 2017). "At day 7 following C. jejuni strain 81–176 infection, colonic mucin-2 expression was down-regulated in mice of either genotype (p < 0.001), but even more distinctly in Nod2−/− IL-10−/− vs. IL-10−/− mice (p < 0.05)." (PMID 28752081, 2017). "It was reported that in natural infection there was a positive correlation between the expression of IL-10 with increasing parasite load and disease progression." (PMID 27094260, 2017). "The inflammatory response induced by infection increased IL-10 and IL-6, activating B cells to secrete IgG." (PMID 29312230, 2017). "Absence of caspase-6 was associated with significantly increased mRNA expression levels of two cytokines in a very early stage after infection, the anti-inflammatory IL-10 and the pro-inflammatory IL-1β, that are marker of poor disease outcome." (PMID 28686630, 2017). "Other studies have also revealed an important role for Mincle in the induction of IL-10 expression in BMDMs or BMDCs upon infection with Malassezia spp." (PMID 28791019, 2017). "In contrast, IL-10+ NK cell numbers remained very low throughout infection (<0.4 × 105 cells per lung)." (PMID 28584007, 2017). "Research showed that TLR2-/- mice presented higher parasite burden than wild-type mice at acute and chronic stages of infection by N. caninum with diminished IFN-γ/IL-10 ratio." (PMID 28798732, 2017). "On the other hand it is known that IL-10 production can reduce the host’s ability to clear infections with various pathogens such as Mycobacterium ssp., Listeria monocytogenes and Leishmania major." (PMID 28686630, 2017). "IL-10 is a major regulator of immunity to infection; it inhibits the activity of Th1 cells, natural killer cells, and macrophages and limits the production of proinflammatory cytokines and chemokines." (PMID 29096690, 2017). "Other groups of mice with higher doses (104 or 105LdWTLLO) infections clearly showed increasing parasite burdens and increasing levels of IL10 at that time point." (PMID 29312315, 2017). "IL-10−/− mice had reduced bacterial loads in internal organs and increased levels of pro-inflammatory cytokines in serum at 5 days of infection." (PMID 28824622, 2017). "The anti-inflammatory cytokine IL-10 also displayed infection-induced increase in expression and variability compared to uninfected control (p ≤ 0.001) in both HT-29 and 8E11 cells." (PMID 29033908, 2017). "Animals infected with the NM showed a decreased level of pro-inflammatory cytokines TNF-α, IFN-ɣ and IL-21 throughout the course of the infection and higher levels of IL-10." (PMID 28650996, 2017). "Next, to demonstrate that IL-10−/− mice clear S. Typhimurium more efficiently than WT mice, bacterial loads were measured at 5 days post infection in ileum, liver, and the spleen." (PMID 28824622, 2017). "Parasite load, as well as nitric oxide (NO), IL-4 and IL-10 production were assessed at 24 and 48 h after infection." (PMID 28767981, 2017). "Infections were associated with splenic volume, leukocyte counts, percentage of Treg cells, and serum levels of CRP, IL-10, and IFN-?" (PMID 27682880, 2017).
infection (continued). "Levels of IL-8 were significantly reduced in both HCT-8 and bovine primary cells, while the levels of INF-γ and IL-10 showed opposite trends in the two cell lines during infection in the presence of Auranta 3001." (PMID 28883891, 2017). "The 0.25 mM NaO treatment increased the IL-10 gene expression (~3-fold), but this effect was reduced after infection." (PMID 28361042, 2017). "The most sensitive cytokine was IL-10 and the most specific was IL-8 in predicting culture-confirmed infections." (PMID 28148470, 2017). "Although T cells become the main IL-10 producers during the acute phase of infection, IL-10 effects on T cell function are usually mediated through paracrine activity on DCs and macrophages." (PMID 28316998, 2017). "Two studies have shown that high IL-10 levels at admission or 6 h following ischemia is an independent predictor of infection." (PMID 28659854, 2017). "As previously reported, IFN-γ+ and IL-10+ double-positive cells regulate immune responses to certain infections." (PMID 28793052, 2017). "At day 7 following peroral C. jejuni strain 81–176 infection, Nod2 mRNA was down-regulated in the colon of secondary abiotic IL-10−/− and wildtype mice." (PMID 28752081, 2017). "The immune response of cows during pregnancy is biased towards the T-helper type 2 environment and responds to the infection by secreting the anti-inflammatory cytokine interleukin-10." (PMID 28542500, 2017). "Accordingly, infection with the lentiviral particles carrying the wild type S protein augmented LPS-induced IL-10 protein secretion, supporting increased immunosuppressive capacity of macrophages exposed to MERS-CoV S glycoprotein." (PMID 28118607, 2017). "A gradual upregulation of IL-10 mRNA expression was observed during early infection, in agreement with our previous finding in buffalo’s serum." (PMID 29216911, 2017). "The footpad swelling result in antigen immunized mice appears to be loosely correlated with the IgG2a/IgG1 ratio before and after parasite challenge and IFN-γ/IL-10 ratio before infection." (PMID 29359145, 2017). "The mRNA expressions of IFN-γ and IL-12 were upregulated at the early stage of infection, and the expression of IL-4, IL-10, and IL-13 increased during the muscle stage." (PMID 29163382, 2017). "In WT mice, we observed a peak of il-10 messenger RNA production in ileum, spleen, and liver after 5 days of infection." (PMID 28824622, 2017). "In a mouse model of WNV infection, IL-10-null mice are reported to be more resistant to the infection as compared to WT mice." (PMID 28151989, 2017). "In accordance, the expression of the anti-inflammatory cytokine IL-10 was neglectable in both infection groups." (PMID 28436493, 2017). "IL-10 production by human macrophages in response to infection is essential for regulating immune responses through both autocrine and paracrine feedback mechanisms." (PMID 28056086, 2017). "The percentage of IL-10+CD4+ T cells in the spleen increased with both infection and bpV(phen) treatment." (PMID 28710387, 2017). "Among the different host factors that play a role in immunosuppression in Cl13 infections, it has been documented that IL-10 production is highly increased in serum." (PMID 28316998, 2017). "These elevated IL-10 levels impair de novo Th1 stimulation and trigger the resolution of the acute phase of infection in which antiviral T cell populations contract." (PMID 28316998, 2017). "Other studies with phenylpropanoid derivatives, demonstrated a correlation between the downregulation of IL-6 and IL-10 with the control of the infection in the Leishmania-infected macrophages." (PMID 28045892, 2017). "IL-10 was elevated 6 weeks after infection, decreased after the seventh week, and returned to normal levels after the tenth week." (PMID 28507072, 2017).
infection (continued). "Early studies showed that infection with H. hepaticus induces colonic regulatory T cells that prevent inflammation in an IL-10-dependent manner and, more recently, that large amounts of IL-23 impede this response." (PMID 29241040, 2017). "Progression from early to late-stage infection was associated with significant increases in IL-6, IFN-γ, and IL-10 concentrations." (PMID 28927234, 2017). "Subsequently, a Th-2 response profile with predominantly IL-10 as anti-inflammatory cytokine was observed after the early phase of the infection, dominated by IFN-γ production." (PMID 28642841, 2017). "In the present study we therefore applied the secondary abiotic murine IL-10−/− infection model to further elucidate the impact of Nod2 in C. jejuni-host interactions." (PMID 28752081, 2017). "In the H. diminuta infected group IL-10 expression is significantly elevated only in the early phase of prepatent period, i.e. six days post infection." (PMID 28771620, 2017). "We found that the frequency of IL-10-producing CD4+ T cells was increased by both infection and PTP inhibition." (PMID 28710387, 2017). "High IL-10 levels act as a regulatory trigger that initiate the resolution of the acute phase of infection in which antiviral T cell populations contract." (PMID 28316998, 2017). "Our study demonstrated that the 0.25 mM NaO treatment induced IL-10 mRNA levels but it was down-regulated after infection." (PMID 28361042, 2017). "Recently, an expanding body of literature provides convincing evidence that B cells exhibit potent immunoregulatory activity via provision of IL10 in a number of auto-immune diseases and pathogen infections." (PMID 28767707, 2017). "As recently shown in mice, the robust immune reaction expressed by the high IFN-γ levels in the acute phase of the infection severely reduces the activity of Tregs in a IL-2 dependent and IL-10 independent manner." (PMID 28642841, 2017). "Serum pro- and anti-inflammatory cytokine levels, including IL-10, peaked during the symptomatic period of infection, coincident with increased frequencies of monocytes and neutrophils." (PMID 28815218, 2017). "In this work, we provide evidence that F. hepatica immune modulates CD11c+ MGL+ cells during infection and that they contribute to the expansion of IL-10-producing T cells and the suppression of Th1-polarized immune responses." (PMID 28360908, 2017). "In silico deletion of IL-10 between the time of infection and 45 days postinfection (PI) increases granuloma sterilization, and this effect is attributable to modest increases in macrophage activation." (PMID 29326718, 2017). "The gene expression of the pro-inflammatory cytokines IL-1β, IFN-γ and TNF-α along with the anti-inflammatory cytokine IL-10 and selected chemokines were significantly up-regulated throughout infection." (PMID 28814754, 2017). "There is no identifiable IL-10 sequence ortholog encoded by MCMV, unlike the primate CMVs; however, various host immune cell types produce IL-10 during both the acute and persistent phases of infection." (PMID 28647908, 2017). "Previous studies have shown that the innate IL-10 production by B cells is required by S. Typhimurium to cause systemic infections in mice, since transfer of B cells from mice unable to produce IL-10 increases their resistance to the infection." (PMID 28824622, 2017). "Mycobacteria-specific IFN-γ responses were highest in mice infected with the virulent isolates early during infection, but at the late stage, these responses were markedly suppressed and in parallel IL-10 responses were increased." (PMID 28182785, 2017). "In fact, expression of IL-10 had already dropped to basal levels at twelve days post infection (Day 43), which was the next time point measured." (PMID 28771620, 2017). "IL-27 and IFN-γ can also induce a Treg population (T-bet+, CXCR3+) that produce higher IL-10 to limit T effector responses, thus reducing infection-induced pathology." (PMID 29118754, 2017).
infection (continued). "T, B, and NK cells expressing IL-10 were barely detected at the steady-state and during the first 2 wk of infection, but were consistently detected after 21 d postinfection, although at lower frequencies compared with those among myeloid cells." (PMID 28584007, 2017). "The levels of IL-10 in HCT-8 cells increased significantly during infection with C. hominis and C. parvum." (PMID 28883891, 2017). "Immuno-regulatory cytokine such as IL-10 was significantly elevated in the three organs tested during the course of infection." (PMID 29034874, 2017). "In the present study we provided direct evidence that IL-10 was detrimental during infection with B. pseudomallei since IL-10 treated mice succumbed earlier than the controls and exhibited significant higher bacterial loads at 48 hours after infection." (PMID 28686630, 2017). "Interleukin 10 (IL-10) expression peaked during the prepatent period, measured at seven days post infection, when larval stages are present." (PMID 28771620, 2017). "IL-10 only seems to play a relevant role, when its production is increased at the site of infection by the administration of sandfly saliva or adenosine and AMP." (PMID 28791011, 2017). "In serum, IFN-γ increased slightly and IL-2 was downregulated during early days of infection, while Th2 cytokines IL-4 and IL-10 increased during the whole intestinal phase." (PMID 29163382, 2017). "BALB/XID mice developed a reduced splenomegaly with diminished splenic parasite burden and lower levels of IL-10 secretion of purified splenocytes at 30 days post-infection, as compared to BALB/c wild-type control mice." (PMID 28626451, 2017). "Despite this increased frequency in IL-10+ cells, relatively low numbers of alveolar and interstitial macrophages and CD11b+ DCs expressing IL-10 were detected in the lungs throughout infection (<1 ×105 cells per lung)." (PMID 28584007, 2017). "In contrast, triggering the activity of T helper 2 along with secretion of IL-4, IL-10 and IL-15 enhances the durability of infection." (PMID 28979355, 2017). "infection induced Th2-biased immune responses with elevated synthesis of IgE and IgG1 and an increased splenocyte production of IL-5, IL-10 and IL-13." (PMID 28606183, 2017). "Our results show that treatment with BNZ affects mRNA expression of IFN-γ, IL-17 and IL-10 in the acute phase of infection by different strains of T. cruzi in the spleen and heart." (PMID 29255475, 2017). "A better understanding at the basic level of IL-10 sources and IL-10 effects on the different components of immunity during infections will allow for precise therapeutic targeting of this pathway." (PMID 28316998, 2017). "Results showed that IL-23, EBI-3 (IL-27 beta subunit), IL-12p40, IL-12p35, IFN-γ, IL-6, and IL-10 mRNA expression were all increased both in the liver and in the spleen during PbNK65 hrfΔ infection as compared to WT infection." (PMID 28831137, 2017). "Our results show a correlation between partial and complete protection against infection with the local secretion of high levels of IL-4, IL-6, IL-10, and IL-17." (PMID 29312230, 2017). "IL-6, IL-8, and IL-10 circulating levels were shown to be higher during infection and further larger studies are needed to confirm these findings." (PMID 28148470, 2017). "A clear increase in IL-10 expression was observed after infection with all isolates in monocytes, even more pronounced by the infection with L.i." (PMID 29358935, 2017). "In later stages of chronic Cl13 infection in mice (i.e., from day 8 after infection and throughout the course of disease), NK cells and virus-specific T cells also play a large role in producing IL-10." (PMID 28316998, 2017).
infection (continued). "Low numbers of IL-10–expressing Foxp3+ Treg cells were detected in the lungs throughout infection (<0.15 × 105 cells per lung)." (PMID 28584007, 2017). "This study showed increased percentages of CD1dhighCD5+IL-10+ B cells post-infection, which is consistent with the elevated IL-10 levels in infected sera." (PMID 28732522, 2017). "In this context, we have recently described that glycans structures produced by F. hepatica participate in the modulation of DC maturation and mediate the production of IL-10 and IL-4 during infection." (PMID 28360908, 2017). "Both cell specific knockouts displayed decreased levels of IL-10 within the lungs at day 12 post-infection similar to the LANCL2−/−." (PMID 28270815, 2017). "A SLA-dependent production of IFN-γ was detected in the popliteal LN culture supernatants from both vaccinated groups, higher in magnitude at week 4 after infection along with IL-10 production." (PMID 28558043, 2017). "Studies demonstrated that the anti-inflammatory cytokines, IL-10 and TGF-β, were presumably related to susceptibility to infection of mice and development of worms in different mice strains." (PMID 28784165, 2017). "Infections were associated with splenic volume, leukocyte counts, the percentage of Treg cells, and serum levels of CRP, IL-10, and IFN-γ." (PMID 27682880, 2017). "The regulatory cytokine produced by Treg, Th2 and some Th1 cells, IL-10, showed significant increase in the spleen at 21 and 28 days post-infection." (PMID 28103263, 2017). "For example, increased IL-10 production has been shown to be beneficial for Bordetella parapertussis (a Bordetella species also infecting humans) infection in mice by limiting a protective IFN-γresponse." (PMID 28076445, 2017). "A number of studies have also demonstrated that let-7 miRNAs levels drop after infection, which in turn increases IL-10 mRNA." (PMID 29118269, 2017). "At baseline, increased expression of inflammatory genes and decreased expression of viral replication inhibitors was evident in asthmatics, and emergence of IL-10 signaling early in infection was evident only in controls." (PMID 28552993, 2017). "In contrast, IL-10 secretion reduced to 462 ± 38 pg/ml, 333 ± 51 and 201 ± 12 pg/ml at 5.0,10 and 15 μM of mahanine compared to 601 ± 40 pg/ml during infection." (PMID 28646156, 2017). "The close correlation of IL-6 and IL-10 responses has also been observed in rodent infection models and has been proposed to reflect the operation of an immunological homeostatic feedback mechanism in the brain." (PMID 28927234, 2017). "Although IL-10 acts as an immune brake on inflammation, its overall effects on antiviral immune responses can be complex and depend on the virus, site of infection, timing of the antiviral immune response, and so forth." (PMID 28316998, 2017). "In healthy individuals, the increased killing was associated with elevated production of IFN-γ, TNF-α and IL-6 in the presence of anti-IL-10 mAb only 6 hours after infection (p < 0.05, <0.001, <0.01 respectively)." (PMID 28216665, 2017). "In human infection, significantly higher levels of IL-10 produced by regulatory T cells are present in patients that do not respond to chemotherapeutic treatment, suggesting an important role of this cytokine in the suppression of host immunity during disease." (PMID 28626451, 2017). "The QRT-PCR results showed that the expression of iNOS and IL-12 peaked at day 3 post-infection and then declined, while the expression of Arg1 and IL-10 slowly increased in the first 3 days and rapidly increased in the following days." (PMID 28824565, 2017). "The total number of IL-10+ cells in the lungs of M. tuberculosis–infected mice greatly increased until day 28 postinfection and then slightly declined as the infection progressed into the chronic phase." (PMID 28584007, 2017).